ROR1 (ROR family WNT receptor 1)
Diseases named in the same sentence as ROR1 in open-access papers (continued):
Sharing a sentence is not in itself a finding about the gene and the disease.
breast cancer (continued). "To study the extracellular spreading of ROR1 and ROR2 in breast cancer, we chose human MCF-7 and MDA-MB-231 as well as murine 4T1 breast cancer cells as model cell lines." (PMID 37430307, 2023). "A phase I trial with ROR1-CART-cells in refractory hematologic malignancies, breast cancer, and lung cancer is ongoing (NCT02706392)." (PMID 36557069, 2022). "We investigated the expression of ROR1 antigen on five human cancer cell lines, including human lung cancer cell A549, HCC827 and NCI-H1975, human breast cancer cell line MDA-MB-231, and human mantle cell leukaemia (MCL) cell line Jeko-1." (PMID 35892876, 2022). "The ROR1 Hinge CAR-T-cells exhibited cytotoxicity against breast cancer cell line MDA-MB-231, lung cancer cell line HCC827, and NCI-H1975, demonstrating the ROR1 Hinge CAR-T was effective against different types of tumors." (PMID 35892876, 2022). "It has demonstrated safety and efficacy in Phase I/II clinical trials for a number of ROR1-expressing malignancies, including chronic lymphocytic leukemia (CLL), mantle cell lymphoma (MCL) and Her2-negative breast cancer (NCT02776917)." (PMID 35456672, 2022). "Although ROR1 is still being evaluated as a CAR target in a clinical trial (NCT02706392) in lung and breast cancer, the clinical efficacy has been very limited." (PMID 35892876, 2022). "The effectiveness of ROR1 CAR T cell therapy was reported in three-dimensional (3D) cell culture models of lung and breast cancer, however, it was also documented that the CAR T cells showed signs of exhaustion already after a short period of time." (PMID 33445713, 2021). "hsa-miR-27b-3p directly targets HSP90AA1 and Fzd7 in NSCLC, ROR1 in gastric cancer, and CBLB/GRB2 in breast cancer to suppresses cell proliferation, migration, invasion, and expression of MET." (PMID 34603447, 2021). "In breast cancer, ROR1 promoted activation of the PI3K/AKT pathway, and high ROR1 expression was correlated with more severe progression of the disease." (PMID 34123850, 2021). "Mediate heterodimerization of ROR1 and HER3 and promote activation of YAP, thus facilitating breast cancer bone metastasis." (PMID 33868368, 2021). "Strictinin, a compound isolated from Myrothamnus flabellifolius was also reported to bind to the intracellular domain of ROR1, which inhibited AKT phosphorylation and survival of breast cancer cells." (PMID 34123850, 2021). "Similarly, a microphysiologic three-dimensional (3D) lung and breast cancer model that closely resembles the architectural and phenotypical features of primary tumors was used to evaluate the antitumor function of receptor tyrosine kinase-like orphan receptor 1-specific (ROR1-specific) CAR T-cells." (PMID 33442419, 2021). "Gene expression of ROR1 was compared between pre- and post-chemotherapy in patients with HER2-negative breast cancer." (PMID 32020017, 2020). "Wnt5a stimulation induces the ROR1-dependent activation and nuclear accumulation of the TAZ protein, thereby enhancing the stemness of breast cancer cells, resulting in improved cell survival, migration and drug resistance." (PMID 31382410, 2019). "The ROR1–PRD was essential for ROR1 to complex with cortactin and increase breast-cancer-cell migration in response to Wnt5a." (PMID 31667337, 2019). "Monoclonal antibody cirmtuzumab against ROR1 inhibited the Wnt5a-stimulated RhoA, YAP/TAZ in PDX breast cancer models, and subsequently reduced metastasis and tumorigenicity." (PMID 31394796, 2019). "We established that the proline at 841 of ROR1 was required for it to recruit cortactin and ARHGEF1, activate RhoA, and enhance breast-cancer-cell migration in vitro or development of metastases in vivo." (PMID 31667337, 2019). "T-DM1 resistance resulted in increased cell surface levels of ROR1 along with CSC-like properties, such as higher percentages of ALDH1+ and CD44+ in ROR1+/T-DM1-resistant breast cancer cells." (PMID 31382410, 2019).
breast cancer (continued). "Further evidence linking the ROR1 and YAP/TAZ pathways to the modulation of CSC self-renewal and drug resistance was provided recently by a study of T-MD1 resistance development in breast cancer." (PMID 31382410, 2019). "ROR1-mediated PI3K/AKT/CREB signaling contributed to the growth and survival of breast cancer cells and this signaling activity was augmented upon stimulation by Wnt5a." (PMID 30832318, 2019). "Previously, we demonstrated overexpression of the homologues receptors ROR1 and ROR2 in brain metastasis of breast cancer patients." (PMID 26862065, 2016). "Promising results in vitro and in vivo using ROR1 as a target to treat CLL, melanoma and breast cancer have been reported." (PMID 25978653, 2015). "Inhibiting ROR1 by a mAb reduces metastatic foci in lungs assessed by bioluminescence and histology with xenografts of MDA-MB-231 breast cancer cells." (PMID 24752542, 2014). "MDA-MB-231 cells silenced for ROR1 expressed lower levels of CREB-target genes, many of which are expressed by breast cancers of patients with aggressive disease." (PMID 22403610, 2012). "In most of the cell lines examined, Ror1 seemed to have a higher or similar expression level compared with Ror2, except in MCF-7 breast cancer cells." (PMID 20587074, 2010). "We found neither ROR1 nor WNT5a upregulation in ER+ models after Dex treatment, highlighting that the output of GR signaling is context and breast cancer subtype-dependent." (PMID 41261233, 2026). "CSCs isolated from patient-derived breast cancer xenografts (ALDH1+/CD44+/CD24Low) had elevated ROR1 levels compared to non-CSC PDX cells." (PMID 40869147, 2025). "Zilovertamab is a mAb against ROR1 which is expressed by cells of numerous solid tumors, including breast cancer, but is absent from most normal postnatal tissues, making ROR1 a good target for treatment." (PMID 40003864, 2025). "Beyond HER2 and TROP2, alternative targets being evaluated for novel breast cancer ADCs in phase I‐II trials include HER3, B7‐H3, B7‐H4, CD166, folate receptor‐α, LIV‐1, nectin‐4, ROR1 (NCT04504916), and ROR2 (NCT03504488)." (PMID 41361931, 2025). "Additionally, treatment of HER2+ breast cancer cells (patient-derived, HCC1954 and MCF7-HER2+) with the HER2-targeting monoclonal antibody trastuzumab (T-DM1), led to a dramatic increase in ROR1 expression." (PMID 40869147, 2025). "Receptor tyrosine kinase-like orphan receptor 1 (ROR1) is an oncofetal antigen that is primarily absent from most adult cell types but constitutively expressed in breast cancer stem cells." (PMID 41348261, 2025). "ROR1 overexpression was observed in chronic lymphocytic leukemia (CLL) which is the most studied malignancy in the context of ROR1 targeted therapies, as well as in triple-negative breast cancer (TNBC) and other aggressive breast cancer subtypes and non-small-cell lung cancer (NSCLC)." (PMID 39551787, 2024). "ROR1 is an onco-embryonic antigen expressed on neoplastic cells of a variety of different cancers, including breast cancer, but not on most normal postnatal tissues, making it a potential target for anti-cancer therapy." (PMID 38408999, 2024). "Targeting ROR1 by small molecules and mAbs has been shown to be an effective therapeutic approach in pre-clinical and clinical studies in various malignancies, such as CLL, MCL, lung, breast cancers, etc.." (PMID 37111634, 2023). "Having detected high levels of vesicular ROR1 and ROR2 expression in breast cancer cells, we asked whether RORs can be transported to surrounding cells via EVs." (PMID 37430307, 2023). "Of note, we did not detect a significant amount of ROR1 or ROR2 on LOs secreted by the investigated breast cancer cells." (PMID 37430307, 2023). "Although not correlated with pCR, high-level expression of ROR1 or ROR2 distinctly identified breast cancer patients with different tumor subtypes with adverse outcomes." (PMID 37029329, 2023).
breast cancer (continued). "In the metastatic breast cancer cell line MDA-MB-231, suppression of ROR1 function led to reduced expression of vimentin, SNAIL-1/2, and ZEB1, but increased levels of E-cadherin, CK-19, and ZO-1; in addition, the ability of MDA-MB-231 cells to migrate and invade decreased." (PMID 36873868, 2023). "ROR1 is present in breast cancer specimens, but not in normal breast tissues, and high expression of ROR1 in breast cancer is associated with aggressive phenotype." (PMID 35712490, 2022). "In breast cancer studies, this strategy mediates antitumor effects on ROR1+ breast cancer without toxicity reaction to normal tissues." (PMID 35935930, 2022). "Here we identify ROR1 as a key upstream regulator of ABCB1 and chemoresistance in breast cancer." (PMID 32020017, 2020). "Overexpression of ROR1 is a prognostic marker in TNBC and the anti-ROR1 antibody cirmtuzumab, originally developed for treating chronic lymphocytic B-cell leukemia, is therefore also in clinical trials for human breast cancer." (PMID 32083079, 2020). "Given the presumed importance of WNT/CTNNB1 signaling in breast cancer stem cell maintenance, it is somewhat counterintuitive that the non-canonical co-receptor ROR1 is emerging as a potential key mediator of chemoresistance in breast cancer stem cells." (PMID 32083079, 2020). "In this regard, we found that cirmtuzumab could block the capacity of Wnt5a to induce ROR1 to complex and phosphorylate cortactin, recruit ARHGEF1, and activate RhoA, thereby suppressing breast-cancer-cell migration/metastasis." (PMID 31667337, 2019). "Many ROR1 mAbs have been designed and demonstrate significant preclinical efficacy; cirmtuzumab (UC-951) is currently in phase I–II of clinical trials for CLL and breast cancer." (PMID 31382410, 2019). "Whether ROR1 can have a similar effect with ROR2 on breast cancer stem cell and what signaling pathway(s) are activated by ROR1 in breast cancer stem cells remains unknown." (PMID 28491097, 2017). "T cells and ROR1 BiTE were co-cultured with either ROR1 positive MDA-MB-231 or ROR1 negative MCF-7 breast cancer cell lines." (PMID 28811962, 2017). "The expression or phosphorylation of ROR1 has shown good correlation with disease stages in patients with chronic lymphocytic leukemia (CLL), ovarian cancer, pancreatic adenocarcinomas, and breast cancer." (PMID 25978653, 2015). "In any case, a sizable fraction of breast cancers expressed ROR1, which was in contrast to the non-neoplastic normal breast tissues." (PMID 22403610, 2012). "These patterns include elevated Fzd2 in metastatic breast cancer, increased ORAI1 in basal-like breast cancer (BLBC), high expression of Vangl2 and ROR1 in BLBC, and overexpression of Syndecan in BC generally." (PMID 40804731, 2025). "There were no discernible differences in the expression of the three prominent breast cancer CSC markers, CD24 (P = 0.066; expression ratio: 0.973), CD133 (P = 0.670; expression ratio:1.02), and CD49f (P = 0.431; expression ratio: 0.907) between the ROR1-high and -low groups." (PMID 38296962, 2024). "To test this hypothesis, we investigated the fate of the oncogenic transmembrane Wnt tyrosine kinase-like orphan receptor 1 and 2 (ROR1, ROR2) delivered via distinct EV subpopulations to breast cancer cells and aimed to unravel their impact on tumor progression." (PMID 37430307, 2023). "In breast cancer, ROR1 was found to be positive in tumor specimens but not normal breast tissues." (PMID 34123850, 2021). "A recent study provided a mechanism by which glucocorticoids may induce metastatic breast cancer and demonstrated that synthetic glucocorticoids such as DEX increased the expression of ROR1, resulting in enhanced metastasis and decreased survival in preclinical models." (PMID 32989221, 2020).
breast cancer (continued). "Moreover, noncanonical Wnt signaling via receptor tyrosine kinases (RTKs), such as ROR1, ROR2, and RYK, activates phosphatidylinositol-3 kinase–AKT (PI3K–AKT) signaling and is involved in numerous cancers including breast cancer, GCs, leukemia, and brain cancer." (PMID 31684152, 2019). "Furthermore, ROR1 is not present in normal mammary tissue, but is overexpressed in breast cancer cells." (PMID 31684152, 2019). "Since it is known that ROR1/2 signaling, especially after stimulation with Wnt5a, requires Dvl for signal transduction, we aimed to analyze which of the Dvl proteins (Dvl1, Dvl2 or Dvl3) might be a good marker for active ROR signaling in breast cancer." (PMID 26862065, 2016). "Moreover, the breast cancer cells that expressed ROR1 generally lacked expression of hormone receptors and/or HER2/neu, which was in contrast to most breast cancer cells lines found to lack expression of ROR1." (PMID 22403610, 2012). "We also found that primary breast cancer tissues that either were poorly differentiated (grade 3), lacked expression of estrogen receptors, or were triple negative, generally expressed higher levels of ROR1 than primary breast cancer tissues without such poor-prognostic features." (PMID 22403610, 2012). "On the other hand, some breast cancer cell lines lacked detectable ROR1 (e.g. MCF-7)." (PMID 22403610, 2012). "Additionally, the MCF-7 breast cancer cell line was identified as ROR1-negative." (PMID 39816690, 2025). "Cirmtuzumab (UC-961), a first-in-class humanized anti-ROR1 mAb, had specific antitumor effect on CLL, breast cancer and pancreas ADC cancer without any off-target activity or toxicity in preclinical tests." (PMID 27830754, 2016). "We found ROR1 was expressed on the estrogen-receptor-negative breast cancer cell lines MDA-MB-231 or MDA-MB-468, but not on the estrogen-receptor-positive breast cancer cell lines MCF-7 or SKBR3." (PMID 22403610, 2012). "Based on the observations of active non-canonical WNT signaling in breast cancer tissue, we compared the expression levels of the known four non-canonical WNT co-receptors ROR1, ROR2, PTK7 and RYK in normal and cancerous breast tissue using the TNMplot database." (PMID 34911552, 2021).
chronic lymphocytic leukemia (65 papers, 2010 to 2026). "ROR1 has been demonstrated to be an important cancer-associated marker for chronic lymphocytic leukemia (CLL)." (PMID 39000112, 2024). "ROR1 is a cell surface receptor modulating neurite growth in the central nervous system, associated with B-cell chronic lymphocytic leukemia in case of increased expression." (PMID 33572894, 2021). "For example, chronic lymphocytic leukemia patients with high ROR1 expression had significantly shorter therapy-free survival and OS, suggesting that ROR1 is associated with more aggressive disease." (PMID 34319035, 2021). "The enhanced expression of ROR1 is associated with malignancies of several tissues, including hematological cancers such as chronic lymphocytic leukemia (CLL), mantle cell lymphoma (MCL), as well as ovarian, breast, prostate, lung, melanoma and colorectal cancers." (PMID 31382410, 2019). "However, we and others have found that ROR1 distinctively is expressed on the leukemia cells of most patients with chronic lymphocytic leukemia (CLL), suggesting that it may play a pathogenic role." (PMID 30568170, 2019). "Increased expression of ROR1 is associated with B-cell chronic lymphocytic leukemia and is constitutively phosphorylated in chronic lymphocytic leukemia (CLL) and Glioblastoma multiforme (GBM)." (PMID 28792525, 2017). "A phase I, single-arm, open-label trial evaluated autologous CAR-T cell therapy targeting receptor tyrosine kinase-like orphan receptor 1 (ROR1) in patients with advanced chronic lymphocytic leukemia and solid tumors (n=21) (NCT02706392)." (PMID 40969260, 2025). "ROR1 overexpression was first identified in B-cell CLL, where it is expressed on the surface of malignant cells in nearly all patients (94%) according to flow cytometry analysis." (PMID 41479906, 2025). "In chronic lymphocytic leukemia, ROR1-specific chimeric antigen receptor T cell therapy elicited rapid antitumor responses in two of three treated patients." (PMID 40723210, 2025). "While ROR1 expression has been described in other tumour entities such as chronic lymphatic leukaemia, triple negative breast cancer and non‐small lung cancer, this is to our knowledge the first study which investigates ROR1 expression in cSCC." (PMID 41355329, 2025). "MiR-15/16 also repressed the expression of ROR1, a receptor for Wnt5a that promotes cell proliferation in leukemia and anoncoembryonic protein expressed in chronic lymphocytic leukemia (CLL) cells, as miR-15/16 expression is inversely related to ROR1 levels." (PMID 38675388, 2024). "ROR1 is, however, expressed in hematologic malignancies and solid tumors, such as chronic lymphocytic leukemia (CLL), mantle cell lymphoma (MCL), diffuse large B-cell lymphoma (DLBCL), melanoma, and NSCLC." (PMID 37111634, 2023). "ROR1 expressed in chronic lymphocytic leukemia (CLL) can also serve as a receptor for Wnt5a, which induces ROR1 to associate with DOCK2 (dedicator of cytokinesis 2) and induces activation of Rac1/2." (PMID 35625853, 2022). "Data on the association between ROR1 and PFS were reported in five studies, including triple-negative breast cancer, chronic lymphocytic leukemia (CLL), and gynecologic cancers." (PMID 36557069, 2022). "For miR-29b delivery to chronic lymphocytic leukemia cells, the oncofetal antigen receptor tyrosine kinase orphan receptor 1 (ROR1) was used for targeting the nanoparticles." (PMID 33672261, 2021). "UC-961, a humanized monoclonal antibody for ROR1 has shown potency in chronic lymphocytic leukemia, ovarian cancer, B-cell lymphoma and breast cancer (clinical trials: NCT03088878, NCT02860676, NCT02222688, NCT02776917)." (PMID 32020017, 2020). "ROR1 protein is overexpressed in several types of leukemia, but prominently in chronic lymphocytic leukemia (CLL), as well as a variety of solid malignancies including: breast, melanoma, pancreas, lung, ovary, colon, and renal cell carcinomas." (PMID 31137681, 2019).